TPI1 (triosephosphate isomerase 1)
Diseases named in the same sentence as TPI1 in open-access papers (continued):
Sharing a sentence is not in itself a finding about the gene and the disease.
intrahepatic cholangiocarcinoma (7 papers, 2021 to 2025). A carcinoma that arises from the intrahepatic bile duct epithelium in any site of the intrahepatic biliary tree. "In liver cancer, proteomic analysis has revealed that TPI1 overexpression is associated with recurrence and poor outcomes in intrahepatic cholangiocarcinoma." (PMID 41429797, 2025). "Recent studies have observed that TPI1 expression is significantly upregulated in intrahepatic cholangiocarcinoma, and that the upregulated TPI1 expression is strongly associated with high recurrences in patients with intrahepatic cholangiocarcinoma." (PMID 34233293, 2021). "TPI1 was discovered through proteomics analysis to be a novel biomarker for predicting intrahepatic cholangiocarcinoma recurrence." (PMID 36809524, 2023). "TPI1 has been proposed as a candidate oncogene, with its overexpression detected in several types of cancers, such as intrahepatic cholangiocarcinoma (ICC), gastric, lung, and prostate cancer." (PMID 35509067, 2022). "TPI1, also named ETS proto-oncogene 1 (ETS1), works as a downstream transcription factor of HIF-1a, which increases in a hypoxic environment and is highly correlated with recurrence rate of intrahepatic cholangiocarcinoma patients." (PMID 35406597, 2022).
liver cancer (6 papers, 2022 to 2025). An epithelial or non-epithelial malignant neoplasm that arises from the liver. "It has been reported that TPI1 has an inhibitory effect on liver cancer." (PMID 37684969, 2023).
colon carcinoma (4 papers, 2019 to 2021). "TPI1 is located in the cytoplasmic and extracellular regions and can serve as a biomarker for the diagnosis of liver metastasis in colon cancer." (PMID 34233293, 2021).
COVID-19 (4 papers, 2021 to 2023). A disease caused by infection with severe acute respiratory syndrome coronavirus 2. "In module 2, enhanced expression of glycolysis (GAPDH and TPI1) and IFN response (IFITM2, IFITM1, IFITM3, IFNGR2, and ISG20) genes in human COVID-19 patients, particularly severely ill patients, may promote the differentiation of unswitched memory B cells into plasmablasts." (PMID 33936072, 2021).
Obesity (4 papers, 2015 to 2025). Accumulation of substantial excess body fat. "However, there is no known link between the remaining genes (including pyk‐2, tpi‐1, 1dh1, to2g5.7, d2063.1, h24k24.3, and sodh‐2) and obesity." (PMID 34401075, 2021).
Parkinson disease (4 papers, 2014 to 2025). A progressive degenerative disorder of the central nervous system characterized by loss of dopamine producing neurons in the substantia nigra and the presence of Lewy bodies in the substantia nigra and locus coeruleus. "Five to seven pQTL were observed for phosphoglycerate mutase 1 (PGAM1), the putative Parkinson disease autosomal recessive early onset 7 variant 1 (PARK7), triose phosphate isomerase (TPI1), peroxiredoxin 4 (PRDX4), malate dehydrogenase 1 (MDH1) and 3-hydroxyanthranilate 3,4-dioxygenase (HAAO)." (PMID 28424047, 2017).
diabetes (3 papers, 2023 to 2025). "A previous study demonstrated that dysregulated ZIP7 modulates TPI1 expression in skeletal muscle cells and is involved in cardiovascular diseases, AD, and diabetes." (PMID 36875704, 2023).
esophageal cancer (3 papers, 2019 to 2025). A primary or metastatic malignant neoplasm involving the esophagus. "For example, in esophageal cancer, high levels of TPI1 autoantibodies in the blood can aid in early disease detection." (PMID 41429797, 2025).
haemolytic anaemia (3 papers, 2018 to 2025). "Despite a slightly elevated MCV and peripheral reticulocyte numbers, heterozygous Tpi1+/F57S mice did not display the characteristics of haemolytic anaemia and were therefore excluded from most tests." (PMID 29720471, 2018).
metastatic tumors (3 papers, 2013 to 2022). "Further, in cervical cancer, the expression of TAGLN2 and TPI-1 was lower in metastatic tumors than in primary tumors." (PMID 23504277, 2013). "Interestingly, histologic analyses of metastatic lung tumors only showed a large increase in CD8 infiltration when TPI-1 was combined with anti-PD-1, consistent with the observed changes in metastatic tumor growth." (PMID 32908154, 2020). "We described that TPI-1 was predominantly identified in metastatic tumors." (PMID 23504277, 2013). "However, the TPI-1 expression in primary tumor was higher than metastatic tumor in cervical cancer." (PMID 23504277, 2013). "On the other hand, the expression of TPI-1 and TAGLN2 was lower in metastatic tumors than in primary tumors in cervical cancer." (PMID 23504277, 2013). "In the present study of clinical tumor samples, we identified the expression of TAGLN2 in primary tumors and we also identified TPI-1 and ENO1 in metastatic tumors, predominantly by LC–MS/MS." (PMID 23504277, 2013). "In this study, expression of TPI-1 and ENO1, which enhances cancer cell survival and proliferation, were higher in metastatic tumors than in primary tumors, and TAGLN2, which suppresses invasion of cancer cells, was lower in metastatic tumors than in primary tumors." (PMID 23504277, 2013). "In addition, the overexpression of TPI-1 in metastatic tumor may not be a necessary character for metastasis." (PMID 23504277, 2013).
oral cancer (3 papers, 2019 to 2025). "We demonstrate that TPI1 is overexpressed in oral cancer tissues and cell lines and that high TPI1 expression correlates with worse patient outcomes." (PMID 40427052, 2025). "To clarify TPI1’s role in oral cancer, we analyzed its expression and correlation with patient outcomes using data from TCGA and GEO." (PMID 40427052, 2025). "To investigate the mechanism of TPI1-induced cisplatin resistance in oral cancer, we performed RNA-Seq following TPI1 silencing in cisplatin-resistant cells." (PMID 40427052, 2025). "To assess TPI1 function in oral cancer, we tested its levels in different cells and results showed that oral cancer expressed higher levels of TPI1 than HOK cells." (PMID 40427052, 2025). "Taken together, these findings support the conclusion that elevated TPI1 expression enables cisplatin-resistant oral cancer cells to escape ferroptotic cell death." (PMID 40427052, 2025). "This upregulation significantly enhanced the proliferation and migration of ccRCC cells, indicating that TPI1 promotes oral cancer progression." (PMID 40427052, 2025). "We then studied TPI1’s role in oral cancer by silencing it in SCC15 cells, confirmed through Western blotting and RT-qPCR." (PMID 40427052, 2025). "Cox regression analyses revealed that TPI1 expression is an independent prognostic factor for oral cancer outcomes." (PMID 40427052, 2025). "Western blot and RT-qPCR analyses confirmed TPI1 expression changes in six paired oral cancer tissues (respectively), indicating that TPI1 may serve as a marker for oral cancer progression." (PMID 40427052, 2025). "To understand TPI1’s role in oral cancer, we studied 107 patients and 28 normal tissues." (PMID 40427052, 2025). "Taken together, we identified TPI1’s role in promoting oral cancer and aiding cisplatin resistance." (PMID 40427052, 2025). "In conclusion, the present study suggests that TPI1 may be a novel regulator of ferroptosis and is also a potential therapeutic target in cisplatin-resistant oral cancer." (PMID 40427052, 2025). "Targeting TPI1 may therefore represent a promising therapeutic strategy to overcome chemoresistance and enhance ferroptosis-based therapies in oral cancer." (PMID 40427052, 2025). "Western blot and RT-qPCR confirmed TPI1 overexpression in oral cancer." (PMID 40427052, 2025). "Therefore, targeting TPI1 may represent a promising therapeutic strategy to restore ferroptotic vulnerability and overcome chemoresistance in oral cancer." (PMID 40427052, 2025). "Taken together, these results suggest TPI1 may function as an oncogene in oral cancer." (PMID 40427052, 2025). "Glycolytic enzymes Aldoa, Hk2, Tpi1, Pgam2, Pfkl, and Pkm2 as well as the PKA-AMPK pathway genes Prkaa2, Pde4a, Pde10a, Ywhag, and Crebbp were downregulated by BRBs during oral cancer chemoprevention." (PMID 31336728, 2019). "In addition, metabolic enzymes such as triosephosphate isomerase 1 (TPI1) and palmitoyl-protein thioesterase 1 (PPT1) have been shown to modulate ferroptosis sensitivity in OSCC cells, further underscoring the intimate link between ferroptosis and the metabolic adaptability of oral cancer." (PMID 41227330, 2025).
prostate carcinoma (3 papers, 2019 to 2024). A carcinoma that arises from epithelial cells of the prostate gland. "Highly expressed TPI1 and the other glycolytic regulators were also suggested to be involved in cell cycle of prostate cancer." (PMID 38102653, 2023).
schizophrenia (3 papers, 2014 to 2016). A major psychotic disorder characterized by abnormalities in the perception or expression of reality. "The glycolytic enzyme GAPDH is a redox-sensitive key enzyme of glycolysis and together with its immediate glycolytic neighbor TPI1 has previously been reported to be differentially regulated in schizophrenia." (PMID 24512814, 2014).
viral infection (3 papers, 2021 to 2025). "Mutations in TPI1 can cause triosephosphate isomerase deficiency, which reduces the immune activity of white blood cells and increases the risk of viral infection." (PMID 33656056, 2021). "The relationship between the expression of TPI1 and virus infection or anti-infectious immunity is unclear." (PMID 39860255, 2025). "An association between TPI1 expression and RSV infection has not been previously reported, but several studies have observed close relationships between viral infections and energy metabolism pathways." (PMID 33656056, 2021).
amyloid (2 papers, 2023). "GPI, PGK1 and TPI1 were elevated in AD compared to AsymAD (p < 0.05), suggesting their elevation is related to cognitive dysfunction as opposed to amyloid pathology." (PMID 37461556, 2023).
anemia (2 papers, 2023 to 2025). A reduction in the number of red blood cells, the amount of hemoglobin, and/or the volume of packed red blood cells. "Previous reports have indicated that hematologic AEs, including neutropenia and anemia, are common in patients who receive FTD/TPI1,4,7." (PMID 37863951, 2023).
bladder cancer (2 papers, 2024 to 2025). "A study also indicated that ALDOA was upregulated in bladder cancer and promoted bladder cancer malignant progression, while there is no report associated with TPI1 in bladder cancer." (PMID 38921479, 2024). "Therefore, we established a BBN-induced bladder cancer mouse model to detect expression of TPI1 in the tumors and the normal bladder tissues." (PMID 38921479, 2024). "Given the fact that fructose and sucrose have different levels between patients with bladder cancer and healthy subjects, further investigations were employed in BBN-induced bladder tumors and normal bladders to confirm a higher expression of TPI1, a critical gene in the fructose metabolism pathway." (PMID 38921479, 2024).
cervical cancer (2 papers, 2013 to 2022). A primary or metastatic malignant neoplasm involving the cervix. "However, the expression of TPI1 was lower in metastatic cervical tumors than in primary cervical cancers." (PMID 35610567, 2022).
cholangiocarcinoma (2 papers, 2021 to 2024). A carcinoma that arises from the intrahepatic biliary tree (intrahepatic cholangiocarcinoma) or from the junction, or adjacent to the junction, of the right and left hepatic ducts (hilar cholangiocarcinoma). "Through the proteomics approach, triosephosphate isomerase 1 (TPI1) was identified as a biomarker for predicting the recurrence of intrahepatic cholangiocarcinoma." (PMID 34095463, 2021).
Ewing sarcoma (2 papers, 2021 to 2024). A small round cell tumor that lacks morphologic, immunohistochemical, and electron microscopic evidence of neuroectodermal differentiation. "In this study, we also observed that the glycolysis-related genes GLCE and TPI1 can be used to construct a prognostic model of Ewing's sarcoma and that their high-risk group corresponds to a significantly poor survival status." (PMID 34233293, 2021). "Here, the prognostic model for Ewing's sarcoma that comprised TPI1 exhibited that the prognosis of patients in the high-risk group is much lower than that of patients in the low-risk group." (PMID 34233293, 2021). "The present study indicated that a high expression of TPI1 in Ewing's sarcoma has an overall poor prognosis compared with low TPI1 expression." (PMID 34233293, 2021). "On the other hand, the rate of positivity staining for immunohistochemical-specific expression of TPI1 was found to be higher in paraneoplastic tissues than in Ewing's sarcoma, and the difference was found to be statistically significant." (PMID 34233293, 2021). "The prognostic model of Ewing's sarcoma constructed using GCLE and TPI1 indicated that survival of the high-risk group is much lower than that of the low-risk group and that GCLE and TPI1 can serve as prognostic biomarkers for Ewing's sarcoma." (PMID 34233293, 2021). "On the other hand, TPI1 was lower in immunohistochemically stained regions of Ewing's sarcoma than in normal tissues (Figure 13C1–13D2)." (PMID 34233293, 2021). "The GLCE expression was significantly higher in Ewing's sarcoma than in paraneoplastic tissues, whereas the TPI1 expression was significantly higher in paraneoplastic tissues than in Ewing's sarcoma, which is consistent with our bioinformatics analysis results." (PMID 34233293, 2021). "We also created a line graph for predicting survival based on GLCE and TPI1 gene expression values, which could be used to predict 1-, 2-, and 3-year survival in patients with Ewing's sarcoma." (PMID 34233293, 2021). "The present study indicated that patients in the high GLCE expression group have a better prognosis compared with the low expression group, whereas the prognostic model of Ewing's sarcoma consisting of GCLE and TPI1 demonstrated a worse prognosis in high-risk patients." (PMID 34233293, 2021).
glioma (2 papers, 2021). A benign or malignant brain and spinal cord tumor that arises from glial cells (astrocytes, oligodendrocytes, ependymal cells). "The results show that PKM and TPI1 are two novel genes suitable for genic expression studies on gliomas." (PMID 34573317, 2021). "The results obtained in this study suggest that the PKM and TPI1 genes could be used as reference genes to normalize and quantify the expression of target genes in pediatric gliomas samples by RT-qPCR." (PMID 34573317, 2021). "Regarding the TPI1 gene, we found that it was not overexpressed in any clinical sample of pediatric glioma." (PMID 34573317, 2021). "Tpi1-KD IG27 glioma cells failed to successfully engraft, and Ldha-KD IG27 glioma exhibited an increased tumor expansion area and cell number." (PMID 33506198, 2021).
hyperglycaemia (2 papers, 2023 to 2025). "Interestingly, our findings indicate no significant downregulation of the GLUT1, GLUT3, and TPI1 gene expression due to hyperglycaemia." (PMID 36830559, 2023).
non-small cell lung carcinoma (2 papers, 2015 to 2023). A group of at least three distinct histological types of lung cancer, including non-small cell squamous cell carcinoma, adenocarcinoma, and large cell carcinoma. "SPP1 with glycolysis genes (GAPDH, ENO1, LDHA, ALDOA, and TPI1) was also expressed in TAMs in non-small cell lung cancer (NSCLC)." (PMID 38347955, 2023).
oral squamous cell carcinoma (2 papers, 2025). "In this study, we investigated the impact of TPI1 silencing on ferroptosis in cisplatin-resistant oral squamous cell carcinoma (OSCC), aiming to elucidate its mechanistic role and therapeutic potential." (PMID 40427052, 2025). "Similarly, in oral squamous cell carcinoma, TPI1 knockout enhanced cisplatin cytotoxicity." (PMID 41206438, 2025).
osteoarthritis (2 papers, 2011 to 2022). A noninflammatory degenerative joint disease occurring chiefly in older persons, characterized by degeneration of the articular cartilage, hypertrophy of bone at the margins and changes in the synovial membrane. "This analysis, and subsequent experimental confirmation, revealed five novel osteoarthritis-associated proteins (PPIB, ASS1, LHDB, TPI1, and ARPC4-TTLL3)." (PMID 35457215, 2022).
pancreatic ductal adenocarcinoma (2 papers, 2020 to 2021). An infiltrating adenocarcinoma that arises from the epithelial cells of the pancreas. "Trisphosphate isomerase 1 (TPI1) is a glycolysis enzyme that is described as a glycolysis-relevant biomarker of pancreatic ductal adenocarcinoma by several researchers; its increase in expression is positively associated with an adverse reaction to chemotherapy." (PMID 33424916, 2020).
small cell lung carcinoma (2 papers, 2022). Small cell lung cancer (SCLC) is a highly aggressive malignant neoplasm, accounting for 10-15% of lung cancer cases, characterized byrapid growth, and early metastasis. "TPI1 was associated with cell cycle, glycolysis, ubiquitin-mediated proteolysis, and small cell lung cancer." (PMID 35509067, 2022). "The TPI1 expression of LUSC was significantly higher than that in LUAD and small-cell lung cancer (P < 0.001 and P = 0.017)." (PMID 35126788, 2022).
triple-negative breast carcinoma (2 papers, 2022 to 2026). An invasive breast carcinoma which is negative for expression of estrogen receptor (ER), progesterone receptor (PR), and human epidermal growth factor receptor 2 (HER2). "We noted that TPI1 was low expressed in triple negative breast cancer cell lines (HCC70 and MDA-MB-468)." (PMID 35509067, 2022).
type 2 diabetes (2 papers, 2018 to 2022). "Plasma miR-193b-3p levels increased in type 2 diabetes cases, and TPI1 levels decreased in both plasma and HepG2 cells with increased miR-193b-3p levels, while extracellular lactate levels did not significantly changed." (PMID 35712251, 2022). "Glycolysis (triosephosphate isomerase 1 and phosphoglycerate kinase 1), citrate cycle (citrate synthase and malate dehydrogenase 2) and type II diabetes mellitus (pyruvate kinase) were among the other pathways identified for these proteins." (PMID 30419808, 2018). "Plasma levels of triosephosphate isomerase (TPI1, a protein involved in the glycolytic pathway) decreased in type 2 diabetes cases (fold change = 1.37, P = 0.002)." (PMID 35712251, 2022).
atrial fibrillation (1 paper, 2025). A disorder characterized by an electrocardiographic finding of a supraventricular arrhythmia characterized by the replacement of consistent P waves by rapid oscillations or fibrillatory waves that vary in size, shape and timing and are accompanied by an irregular ventricular response. "A reduction of energy-producing proteins including glycolysis-related proteins, such as ALDOA and TPI1, and mitochondrial proteins, such as oxidative phosphorylation complexes, has also been reported in the arterial tissue of patients with atrial fibrillation." (PMID 41468454, 2025).
bladder tumors (1 paper, 2024). "BBN-induced bladder tumors confirmed higher expression of TPI1, a critical gene in the fructose metabolism pathway." (PMID 38921479, 2024).
brain glioma (1 paper, 2021). A malignant glioma that involves the brain. "Thus, we propose PKM and TPI1 as suitable reference genes in gene expression studies in brain glioma biopsies." (PMID 34573317, 2021).
candidiasis (1 paper, 2021). Infection with the organism Candida. "It was also shown in prior reports that antibodies against Tpi1 were present in the sera of systemically infected mice and in the sera of patients with candidiasis, thus classifying Tpi1 as an immunoreactive protein." (PMID 34210257, 2021).